HGF (hepatocyte growth factor)
Diseases named in the same sentence as HGF in open-access papers (continued):
Sharing a sentence is not in itself a finding about the gene and the disease.
tumor (continued). "However, MET receptor activation was also evident in scattered tumor cells in the absence of adjacent Iba1high TAMs suggesting paracrine mechanisms or additional sources of HGF such as immune cells or astrocytes." (PMID 38386085, 2024). "In addition, IL-6 could also promote tumor cell survival, growth, proliferation, transformation, invasion, and migration by upregulating TGF-β and activating the STAT3 and HGF/c-MET pathways." (PMID 36831664, 2023). "In our setting, macrophage cultures from hypoxia-susceptible rats, but not the tolerant group, responded to LPS stimulation by increased expression of HGF protein, which under in vivo conditions could promote the triggering of ERK1/2/MAPK and PI3K/AKT signaling pathways in cells and tumor growth." (PMID 37842051, 2023). "Hence, overactivity HGF-c-MET axis, triggered by CAF responses to RT, stimulates tumor progression." (PMID 37607935, 2023). "The EV release of bioactive molecules, such as platelet-derived growth factor (PDGF), hepatocyte growth factor (HGF), interleukin-6 (IL6), proteases, and miRNAs by CAFs into the extracellular matrix further supports their importance in cell–cell communication within the tumor microenvironment." (PMID 37760975, 2023). "Not only do CAFs secrete HGF, CTGF, basic fibroblast growth factor (bFGF) and other cytokines, which promote tumor metastasis, but the corresponding tumor cells or other types of cell-secreted cytokines can also promote the activation of CAFs to stimulate TME remodeling and increase tumor invasion." (PMID 37978384, 2023). "It is believed that p-MET is a promising therapeutic target due to its elevated expression in multiple TNBC subtypes, which indicates that, by inhibiting the HGF/MET signaling pathway, foretinib may exert an antitumor effect through a direct cytotoxic effect on tumor cell proliferation." (PMID 36614199, 2023). "Notably, HGF/c-MET inhibition decreases TGF-β secretion by cancer cells, resulting in an increase in cytotoxic T-cell infiltration, thus contributing to cancer cell death in tumours." (PMID 37354984, 2023). "Since HGF activated MET/GAB1 pathway in entrectinib‐treated HCC78 cells, the timing of tumor cell lysate harvesting might not be optimal for detecting HGF‐induced MET phosphorylation." (PMID 36416133, 2023). "However, inhibiting VEGFA could negate its suppression of HGF-dependent MET phosphorylation and tumor cell migration and lead to a more invasive phenotype." (PMID 37214395, 2023). "Therefore, tumour cells also use its activity to promote tumour progression, but, unlike melanocytes, melanoma cells are able not only to express c-MET, but also to release HGF in an autocrine manner for self-stimulation." (PMID 37022605, 2023). "Additionally, Hh pathway-activated tumor cells can rely on downstream inducers of MMPs, including MMP2 and MMP9, to degrade collagen IV, collagen VII, and glycoproteins, thereby modifying the ECM and releasing HGF bound to the matrix." (PMID 37919751, 2023). "Our results revealed that plasma HGF rather than tumor HGF might be a reliable biomarker for LM and inferior survival in SCLC, and its potential value for noninvasive disease monitoring needs to be further explored." (PMID 37828456, 2023). "METex14 single alteration was sufficient but required HGF to drive MET‐dependent sustained phosphorylation and signalling, enhanced cell motility, anchorage‐independent survival, changes in gene expression and in vivo tumorigenesis in humanised HGF knock‐in mice, sensitising tumours to MET‐TKIs." (PMID 36799689, 2023). "MET is an RTK activated by hepatocyte growth factor (HGF) and mediates several physiological processes, such as embryogenesis and tissue repair; aberrant activation of MET by genetic alterations plays an important role in the proliferation, invasion, and metastasis of tumor cells." (PMID 36224343, 2022).
tumor (continued). "In conclusion, Erk activation is induced by HGF directly, enhancing tumor proliferation; however, the enhancement of proliferation is considered to accelerate the misincorporation of 5-FU metabolites into DNA and RNA, which is further augmented by UPP1 overexpression, induced by HGF." (PMID 36012373, 2022). "Therefore, CAFs may contribute to HCC tumor progression by producing growth factors (EGF, FGF, HGF, and TGF-β), chemokines (SDF-1), cytokines (IL-6), and metalloproteinases (MMP-3 and MMP-9)." (PMID 35158892, 2022). "NSCLC patients who use tyrosine kinase inhibitors for an extended period may have an increased generation of lactate by their tumor cells, which stimulates TME cells to produce more hepatocyte growth factor (HGF), further increasing cancer resistance and development." (PMID 35733921, 2022). "HGF is an activator of the MET pathway, which has been associated with peripheral expansion of neutrophils, as well as with immunosuppressive activity of these cells and lack of tumor T lymphocyte infiltration." (PMID 36010840, 2022). "HGF could activate the c-Met signal transduction cascade, drive both cancer cell invasion and metastasis and allow/proliferate/induce tumor cellular survival in bloodstream due to an absence of anchorage." (PMID 35568918, 2022). "Additional factors that may lead to the mobilisation of myeloma cells through the acquisition of an EMT-phenotype include the increased concentration of cytokines such as IL-6, TNFα, VEGF, HGF and IGF-1 in the tumour microenvironment during the symptomatic phase of the disease." (PMID 35203300, 2022). "It seems that tumor patients developing proteinuria after TKI treatment cannot benefit from HGF, but this may partly explain the predictive role of TKI-induced proteinuria on anticancer efficacy —that is, patients with proteinuria may have low levels of HGF." (PMID 33921219, 2021). "In our study, we showed that HGF from liver environment is responsible for the activation of cholesterol biosynthesis pathway in liver metastases of CRC, which supports the model that tumor cells undergo dynamical metabolic adaptation to local conditions of metastatic organ." (PMID 33995676, 2021). "Furthermore, fibroblasts are a large source of growth factors and cytokines, including stromal cell-derived factor 1 (SDF1), hepatocyte growth factor (HGF), and vascular endothelial growth factor (VEGF), which all promote tumor growth and contribute to chemotherapy resistance." (PMID 34900703, 2021). "Factors that can promote the anti-tumor neutrophil phenotype include chemokines (e.g., CXCL2, CXCL5, CXCL8, CCL2, CCL3, CCL5, CXCL12 (SDF-1), CXCL16 and IL-8) alone or together with G-CSF/GM-CSF, TNFα, IFNβ, IFNγ, IFNγ together with TNFα, Resolvin D1, hepatocyte growth factor (HGF) and IL-17." (PMID 34572138, 2021). "The HGF-dependent phosphor-rylation of the MET receptor is correlated with an enhanced potential of malignant cell migration and invasion, introducing this pathway as a remarkable therapeutic target for the suppression of invasion and the spread of tumor cells." (PMID 34217156, 2021). "An interesting possibility would be to look for variants of EGF, HGF, IGF-1, and VEGF as has already been done with other molecules; this would foster the regeneration process or at least not hinder it, without affecting tumor progression." (PMID 34572344, 2021). "In other solid cancers, neutrophils support tumour growth by contributing to genetic instability by releasing reactive oxygen species (ROS) and secreting growth factors, such as epidermal growth factor (EGF), hepatocyte growth factor (HGF), and platelet-derived growth factor (PDGF)." (PMID 34830780, 2021). "At the same time, tumor cells release chemoattractant proteins that recruit TAMs, such as CCL2, CSF-1, granulocyte–macrophage colony stimulating factor (GM-CSF), hepatocyte growth factor or scatter factor (HGF/SF), stroma-derived factor 1 (SDF-1), and glial cell-derived neurotrophic factor (GDNF)." (PMID 33766119, 2021).
tumor (continued). "CAF with tumor-promoting functions secrete growth factors (HGF, IGF1, CTGF, PDGF, VEGF, LIF), cytokines (IL-1, IL-4, IL-6, IL-8, IL-10, TGF-β), and chemokines (CCL2, CCL5, CXCL5, CXCL9, CXCL10, CXCL12), WNT5α, and bone morphogenic protein 4 (BMP4), which promote tumor progression." (PMID 35008832, 2021). "Chemokines like TNFα, IL-1, HGF, IFN-α, and their receptors activate MAPK, nuclear factor-kappa-β (NF-kB), and phosphatidylinositol-3 kinase (PI3K)/Akt, signal transducer and activator of transcription (STAT) pathways involved in cell proliferation, survival, invasion, metastasis, and tumor growth." (PMID 33925575, 2021). "Therefore, drugs targeting EGF, IGF-1, and HGF may critically disrupt not only tumorigenesis and progression of HCC but also angiogenesis, and counteract the metastasizing potential of the tumor." (PMID 34572344, 2021). "However, regardless of H3122/HGF and H3122 xenografts, metformin in combination with alectinib produced a significantly greater inhibition of tumour growth compared with that in the single agent groups (p < 0.05)." (PMID 32041944, 2020). "Growth factors such as VEGF and hepatocyte growth factor (HGF), and epidermal growth factor receptor (EGFR) have been observed to be overexpressed in many cancers including HCC, as they play a crucial role in different mechanisms involving tumor proliferation, metastasis and angiogenesis." (PMID 32722054, 2020). "Additionally, Indo5, selectively abrogating HGF-induced c-Met pathway activation and brain-derived neurotrophic factor (BDNF)/nerve growth factor (NDF)-induced Trks signaling activation, significantly inhibits HCC tumor growth in xenograft mice." (PMID 32117981, 2020). "Hepatocyte growth factor (HGF)/c-mesenchymal-epithelial transition factor (c-Met) axis is an essential mediation axis that regulates cellular biological events including cell proliferation, migration and morphogenesis and tumor biological processes such as angiogenesis and drug resistance." (PMID 32083078, 2020). "Some of the most well-studied lymphangiogenic factors that govern tumor lymphangiogenesis are the vascular endothelial growth factor (VEGF-C/D and VEGFR-2/3), neuroplilin-2 (NRP2), fibroblast growth factor (FGF), and hepatocyte growth factor (HGF), to name a few." (PMID 33172072, 2020). "Contrastingly, basophils may exert pro-tumor activities, through release of pro-angiogenic and lymphangiogenic mediators, such as VEGF-A and VEGF-B, CXCL8, angiopoietin-1, hepatocyte growth factor, and tryptase, and may suppress anti-tumoral immune responses, such as through T-reg interactions." (PMID 32645919, 2020). "Similarly, in nonsmall‐cell lung cancer, responders to 2 months of RT had higher levels of microRNA‐198 in the tumour than nonresponders, and HGF/Met signalling was suggested to be a crucial mediator of this effect." (PMID 32946618, 2020). "Interestingly, hepatocyte growth factor (HGF) induced HDGF in a dose-dependent manner, and HDGF induced the expression of VEGF, thus suggesting that HDGF may be involved in tumor growth by means of its cooperation with these growth factors." (PMID 32545762, 2020). "PDX could not mirror the human in vivo situation properly because the murine HGF deriving from the tumor microenvironment did not activate the human HGFR as reported also by others." (PMID 31861874, 2019). "For example, HGF has been identified as an essential factor in the CAF-mediated resistance to lapatinib in HER2+ breast cancer; and CAFs may also act as a physical barrier against anti-tumor drugs and decrease their availability to tumor cells." (PMID 30927930, 2019). "However, treatment with HGF decreased the percentage of CD8+ T cells and the secretion of IFN-γ in the co-culture system, indicating that HGF weakens the cytotoxicity of T cells toward tumours." (PMID 31747941, 2019). "By ablating HGF expression in vivo, CAFs failed to promote tumor growth in nude mice." (PMID 31106200, 2019).
tumor (continued). "Growth signals from the tumor stroma, such as TGF-β (transforming growth factor), EGF (epidermal growth factor), FGF (fibroblast growth factor), PDGF (platelet-derived growth factor), IGF (insulin growth factor) and HGF (hepatocyte growth factor), are responsible for triggering EMT in cancer cells." (PMID 29416704, 2018). "Finally, since HGF/MET stimulation increases the proliferation of NKTCL cells in vitro, MET inhibition again displayed a dual role: direct tumor killing for MET-dependent cell survival, and anti-tumor immune activation." (PMID 30441809, 2018). "For example, the HGF secreted by CAFs acts on tumor cells stimulating them not only to proliferate, invade and metastasize but also to produce a variety of HGF-inducers, such as bFGF, IL-1β, TGF-α, PDGF and prostaglandin E2 (PGE2), that act on stromal fibroblasts." (PMID 30352967, 2018). "Therefore, the HGF/c-MET feedback loop regulates tumor proliferation, invasion and migration and may be a novel target for growth factor-induced tumor growth." (PMID 30567565, 2018). "In light of these considerations, therapies targeting the MET/HGF pathway in a context of expedience may impair the survival and the ability to disseminate of cancer cells, but are not expected to reduce tumor growth." (PMID 30544501, 2018). "Among them, transforming growth factor-α and -β (TGF-α, TGF-β), hepatocyte growth factor (HGF), Platelet derived growth factor (PDGF), and vascular endothelial growth factor (VEGF) have been shown to establish a micro-environment which is favourable to tumor cell growth, migration and invasion." (PMID 29599818, 2018). "Moreover, NAC-HCPS significantly inhibited tumor growth and vascularization of subcutaneously implanted 3LL, an effect likely related to its ability to inhibit the endothelial cell growth stimulated by VEGF165, FGF2, or HGF." (PMID 30413079, 2018). "Hepatocyte growth factor (HGF)/ mesenchymal-epithelial transition factor (c-MET) signaling is involved in complex cellular programs that are important for embryonic development and tissue regeneration, but its activity is also utilized by cancer cells during tumor progression." (PMID 30513872, 2018). "HGF interacts with c-MET via an autocrine and/or paracrine signaling loop and participates in a variety of biological responses, such as embryonic development, epithelial branching morphogenesis, postnatal organ regeneration, wound healing, and tumor development." (PMID 28817103, 2017). "Global increase of hepatic interleukin-1β, interleukin-6, tumor necrosis factor-α and hepatocyte growth factor was detected in low-fat/high-carbohydrate and high-fat with respect to standard diet fed mice as well as in tumor with respect to non-tumor bearing mice." (PMID 28881825, 2017). "Furthermore, a member of the inhibitor of apoptosis protein, Survivin, was proven to be upregulated by HGF-c-MET pathway, which could promote the tumor progression." (PMID 29254283, 2017). "Monitoring HGF-mediated functions on tumor growth in xenograft models is limited by the fact that murine (stromal) HGF is not able to efficiently induce cMET signaling in human tumor cells." (PMID 29228696, 2017). "Future studies including a control group with patients not treated with an EGFRI will help to further clarify the role of HGF as a predictive or prognostic biomarker, also confirming in larger cohorts if the predictive value is independent of the specific tumor site." (PMID 28456787, 2017). "Furthermore, administration of tracers based on the HGF ligand such as 64Cu-HGF, as well as the bivalent antibody DN30, might have the unwanted result of stimulating tumour growth by activating c-MET." (PMID 28315949, 2017). "The mRNA and protein levels in HCC tumor cells are significantly higher than those in para-carcinoma tissue (P<0.01), and the overexpression of VEGFA could promote paracrine secretion of hepatocyte growth factor (HGF)." (PMID 28903454, 2017).
tumor (continued). "We also determined that tumor-derived HGF, not systemic HGF, may be required to convey resistance to BRAF inhibition in vivo and that resistance could be reversed following treatment with AMG 337, a selective MET inhibitor." (PMID 28147313, 2017). "In the syngeneic MC38 model, treatment with either the anti-VEGF or the anti-HGF DARPin® molecules inhibited tumor growth but MP0250 gave significantly greater inhibition, the implication being that both growth factors contribute to the growth of this tumor and its vasculature." (PMID 29228696, 2017). "Met, whose natural ligand is Hepatocyte Growth Factor (HGF), can recruit various adapter proteins or direct kinase substrates through its Src-Homoloy-2 (SH2) domain such as PI3K, Src or Ras and is implied in tumor growth, survival, invasion and in matrix remodeling." (PMID 28446239, 2017). "Since HGF is an angiogenesis inducer and has been demonstrated to induce expression of vascular endothelial growth factor (VEGF) as well, it might also stimulate angiogenesis in DLBCL, thereby promoting tumor growth." (PMID 27923392, 2016). "However, not much is known regarding miRNA-200a expression in tumor stromal fibroblasts and the relationship between miRNA-200a and HGF in cancer." (PMID 27374174, 2016). "However, our data suggesting that MCT1 regulates tumor cell motility and HGF/c-Met signaling independent of transporter activity is novel in that it begins to establish a previously undefined function of MCT1." (PMID 27127175, 2016). "Thus the tumor mass is no longer exposed to transgenic HGF for lack of differentiated muscle cells, as shown by the absence of expression of the eGFP reporter in the tumors." (PMID 26987019, 2016). "Therefore it is likely, that the produced amphiregulin is provided for other cell types of the tumor stroma, which did not get in contact with HGF before or amphiregulin is provided for cell types, where the EGFR is not blocked by HGF." (PMID 25884419, 2015). "Platelets may also promote tumor cell growth by secreting several angiogenic and tumor growth factors, such as thrombospondins, endostatin, vascular endothelial growth factor (VEGF), platelet-derived growth factor (PDGF), and hepatocyte growth factor." (PMID 25955026, 2015). "Given that HGF can activate the PI3K/AKT signaling, we hypothesize that HGF may regulate the GRP78 expression by activating the PI3K/AKT signaling and GRP78 may be the key factor for development of chemoresistance in tumor cells." (PMID 26115510, 2015). "Indeed, within the primary tumor microenvironment, the stromal cells provide potent oncogenic signals, such as TGF-β, HGF, epidermal growth factor (EGF), Wnt, and β-fibroblast growth factor (FGF), which stimulate cancer cell proliferation, survival, and invasion, thus facilitating metastasis." (PMID 28536400, 2015). "Additionally, recent research has demonstrated that VEGF could negatively regulate HGF/c-MET axis through a MET/VEGFR2 heterocomplex, therefore suppress tumor invasion." (PMID 26620439, 2015). "Murine HGF binds to, but does not fully activate human Met; to circumvent this obstacle to mimicking paracrine HGF driven tumor growth in humans, we used SCID mice that are genetically engineered to express only human HGF (hHGF; hHGFki/ki,SCID/SCID, also known as Hgftm1.1 (HGF)Aveo)." (PMID 25534569, 2014). "Increased hepatocyte growth factor (HGF) and epidermal growth factor (EGF) levels may be an additional explanation for the accelerated tumor growth due to the stimulatory effects that HGF and EGF exhibit on tumor cells." (PMID 24940392, 2014). "Changes in tumor growth could not be explained by measures of HGF action including phospho-AKT or phospho-S6." (PMID 25072025, 2014). "Thus, an increased HGF level in the ADSC-SCCs microenvironment, as shown in our experiment, might also promote tumor progression in an in vivo setting." (PMID 24887580, 2014).